CXCR2 (C-X-C motif chemokine receptor 2)
Diseases named in the same sentence as CXCR2 in open-access papers (continued):
Sharing a sentence is not in itself a finding about the gene and the disease.
cancer (continued). "These facts indicate that a CXCR2-mediated signaling pathway is closely associated with cancer progression." (PMID 24376747, 2013). "Recently, few studies have shown the relationship between CXCR2 gene polymorphisms and human cancer." (PMID 20540789, 2010). "In agreement with our findings, several studies reported a relationship between IL-8 (-251) T/A and CXCR2 (+1208) C/T genes polymorphisms and human cancer." (PMID 20540789, 2010). "CXC chemokine receptor 2 (CXCR2), a G-protein-coupled receptor, has been implicated in promoting cancer cell proliferation, invasion, metastasis, angiogenesis, chemoresistance, and maintaining cancer stem cells." (PMID 41155662, 2025). "CXCR2 is also a receptor for IL-8 and this cytokine has also been linked to cancer cachexia." (PMID 41392310, 2025). "Meanwhile, the receptor CXCR2 was predominantly expressed by cancer-associated fibroblasts." (PMID 41259383, 2025). "Increased CXCR2 expression has been linked to poor prognosis in various cancers." (PMID 36140779, 2022). "This was because apart from macrophages, CSF1R signals in cancer-associated fibroblasts leading to macrophage inflammatory protein 2 secretion triggered the manifestation of suppressive and angiogenic properties in macrophages upon CXCR2 paracrine activation." (PMID 35315360, 2022). "However, an elevated level of CXCR-2 is linked to diminished expressions of E-cadherin and β-catenin in cancer tissues, attributing to the part played by CXCR-2 in EMT." (PMID 34336101, 2021). "In conclusion, CXCR2 was a risk factor of cancer prognosis with a wide application in terms of both OS and PFS except for digestive tract cancer, which could guide clinical treatment of various cancers." (PMID 29599927, 2018). "Our study demonstrated that the crosstalk between CXCL1 from cancer cells and CXCR2 of stromal fibroblasts cells might be associated with tumor progression." (PMID 28575019, 2017). "Other cancer types also indicate that CXCR2 is closely associated with cancer progression." (PMID 27723802, 2016). "CXCR2 mRNA was almost deficient in normal tissues but noticeably present in cancer tissues." (PMID 26087179, 2015). "The loss of p21 expression has been observed in several types of cancer, and the loss of p21 expression in hPTTG1/CXCR2 double-positive samples (34 (45.33%) of 75) provides a reasonable explanation for how hPTTG1-overexpressing cancer cells manage to escape senescence." (PMID 22789011, 2012). "Similarly to IL-6, the CXCR2 (C-X-C motif chemokine receptor 2)/IL-8 axis induced by KRAS was shown to be crucial for promoting phenotype alterations of CAFs (cancer-associated fibroblasts) and increased secretion of pro-tumoral cytokines that eventually promoted the development of PDAC." (PMID 40427186, 2025). "Moreover, SLC6A14 induced CXC motif chemokine ligand 8 secretion via synaptotagmin-like 4-mediated exocytosis, paracrinally activating CXCR2 signaling in cancer-associated fibroblasts to enhance mitochondrial fission and amino acid recycling, supporting PDAC progression." (PMID 41444422, 2025). "Moreover, the activation of NF-κB by CXCR2 causes cancer cell migration." (PMID 35216283, 2022). "According to one study, CXCL8 stimulates NET production by interacting with CXCR2, which in turn increases the migration and proliferation of cancer cells." (PMID 41503514, 2026).
cancer (continued). "The overexpression of CXCL1 and CXCL2 in cancer cells has been shown to attract neutrophils into tumors, leading to chemoresistance, a process that can be mitigated by blocking CXCR2." (PMID 41486114, 2026). "C-X-C motif chemokine receptor 2 (CXCR2) expression is upregulated in several cancer types including NSCLC." (PMID 40006675, 2025). "Cancer cells have high expression of CXCR2, so CXCL1 will bind with high affinity to its receptor on the membrane of cancer cells." (PMID 40427171, 2025). "CXCR2 activation by IL-8 has been extensively investigated in cancer and other inflammatory, angiogenic, and fibrotic diseases." (PMID 41176546, 2025). "CXCR2 is overexpressed in several cancer types, including breast, prostate, colorectal, and lung cancers." (PMID 40124384, 2025). "IL-8 has been demonstrated to recruit MDSCs and enhance immune escape in cancer via C-X-C motif chemokine receptor 2 (CXCR2) signaling." (PMID 41514551, 2025). "CXCR2 antagonism is a promising therapeutic approach for the treatment of inflammatory diseases and cancer." (PMID 40727104, 2025). "Targeting the human chemokine receptor (CXCR2) holds significant potential in treating inflammatory diseases and cancer." (PMID 40727104, 2025). "CXCR2 exerts its pro-metastatic effects through various mechanisms, including the promotion of cancer cell migration, invasion, and angiogenesis." (PMID 40124384, 2025). "In glioblastoma, the vascular system maintains the cancer stem cells (CSCs) via IL-8/CXCR2 signaling." (PMID 41155662, 2025). "This review examines the therapeutic potential of targeting CXCL1 and its receptor, CXCR2, in cancer treatment." (PMID 40427171, 2025). "We postulate that the role of CAF-secreted CXCL5 in cancer cachexia is due to activation of the CXCL5 receptor CXCR2 in skeletal muscle." (PMID 41392310, 2025). "The CXCR2+ cell populations that are recruited play a crucial role in the malignant development of malignancies and can be targeted for cancer treatment." (PMID 39670859, 2025). "CAFs in turn, secrete C-X-C motif chemokine 5 (CXCL5), which binds to c-x-c motif chemokine receptor 2 (CXCR2) on cancer cells, resulting in PI3K pathway activation and downregulation of PD-L1." (PMID 40362630, 2025). "The CXCR2 chemokine signaling axis controls a range of tumorigenic processes, including cancer cell proliferation, invasion, metastases, self-renewal ability, and angiogenesis." (PMID 41155662, 2025). "This CXCL1/CXCR2 axis in CAFs mediates cancer cell invasion via induction of IL-1β, revealing a reciprocal dependency between CAFs and cancer cells within the OSCC microenvironment." (PMID 41445742, 2025). "Our results show that CXCL5 treatment can induce myotube atrophy and CXCR2 expression is upregulated in the skeletal muscle of mice transplanted with cancer cells plus CAF." (PMID 41392310, 2025). "The immunotherapeutic potential of the CXCL8-chemokine/CXCR2-chemokine-receptor system is currently being explored in numerous human cancers." (PMID 38900374, 2025). "In particular, increasing attention has focused on selective CXCR2 antagonism as a therapeutic strategy for cancer and inflammatory diseases." (PMID 38900374, 2025). "Our findings confirm the involvement of the CXCL8/CXCR2-axis in promoting pro-tumorigenic effects in TC cells, further demonstrating its immunotherapeutic significance in human cancer." (PMID 38900374, 2025). "The IL-8/CXCR2 axis has attracted growing interest, particularly for its role in sustaining cancer stem cell populations and promoting immune evasion." (PMID 41007766, 2025). "Pseudotime analysis implicates IL1β/CXCL8/CXCR2 axis in the progression of neutrophils from health to cancer and metastasis, with effects on T-cell effector function." (PMID 38358352, 2024). "Other pairs, such as those mediated by CXCR2, display cancer subtype-specific patterns of both DE and correlation with patient survival." (PMID 38723607, 2024).
cancer (continued). "CXCR1 and CXCR2 are expressed in various cell types including immune cells, fibroblasts, endothelial cells, osteoclasts, and cancer cells." (PMID 39766038, 2024). "The CXCLs (i.e., CXCL1, 2, 3, 5, 7 and 8)-CXCR2 signaling axis is involved in the recruitment of MDSCs in various types of cancers, including CRC." (PMID 38750114, 2024). "Numerous studies have supported the importance of CXCR2 ligands-CXCR2 axis for cancer growth and development using genetic ablation of mouse CXCR2 or blockade of CXCLs or CXCR2." (PMID 38786066, 2024). "Some studies have suggested that the activation of CXCR2 and/or increases in IL-8 promote stem-like properties in cancer cells, including enhanced self-renewal and resistance to differentiation." (PMID 39199570, 2024). "It is known that the ligands of C‐X‐C motif receptor 2 (CXCR2) are highly secreted by human cancer cells, including pancreatic cancer." (PMID 39245957, 2024). "Despite contradictory reports, high CXCL1, CXCL2, CXCL8, CXCR2 levels and accordingly high neutrophil levels correlate with cancer aggressiveness and poor patient survival in general." (PMID 38786066, 2024). "CXCR2 antagonists were initially designed to cure pulmonary inflammatory diseases and are gradually being used in cancer treatment with some success in preclinical studies (NCT02499328, NCT02583477)." (PMID 39529085, 2024). "IL-8, acting through C-X-C chemokine receptor type 1 (CXCR1) and type 2 (CXCR2), modulates multiple signalling pathways, enhancing the angiogenesis, proliferation, and migration of cancer cells." (PMID 39199570, 2024). "Apart from helping to maintain homeostasis and physiological communication, both CXCR1 and CXCR2 have been shown to be aberrantly expressed or activated in various cancer types, including PCa." (PMID 39766038, 2024). "This cluster was also enriched for the chemokine receptor CXCR2, which is a commonly studied target in murine models of cancer influencing metastatic burden, suggesting these neutrophils identified are functionally relevant." (PMID 38358352, 2024). "Here, we provide data that supports the role of neutrophil-specific CXCR2 expression in enhancing colorectal liver metastasis in KRAS mutant cancer." (PMID 38358352, 2024). "The angiogenic properties of CXCL1, EPC, and CXCR2+ cancer stem cells can compensate for blocking VEGF activity during anti-angiogenic therapy, which leads to resistance to treatment." (PMID 38673949, 2024). "CXCL3 binds to CXCR2, which is expressed in endothelial cells, various immune cells and cancer cells." (PMID 37465363, 2023). "Our results demonstrated that CXCR2 blockade sensitized cancer cells to DTX via decreasing cancer cell stemness." (PMID 36859354, 2023). "KT alleviates the invasion of cancer cells from blood vessels to bone by inhibiting CXCL5/CXCR2 and CXCL12/CXCR4." (PMID 36674719, 2023). "The chemokine CXCL8 (also known as interleukin-8, abbreviated IL-8) and its G-protein-coupled receptors CXCR1 and CXCR2 are crucial elements in this process, and also the development of many cancers." (PMID 37433790, 2023). "Neutrophil CXCR2 enhances neutrophil migration into areas that support cancer, while CXCR2 reduction in neutrophils enhances ROS generation and the pro-cancer effect." (PMID 37892995, 2023). "The inhibition of CXC chemokine receptor 2 (CXCR2), akey inflammatorymediator, is a potential strategy in the treatment of several pulmonarydiseases and cancers." (PMID 37523859, 2023). "The pathways activated by CXCR2 increase the proliferation of cancer cells and exhibit anti-apoptotic properties." (PMID 37686093, 2023). "Overall, we demonstrated that treatment with TAS2R9-targeting liposomes loaded with a CXCR2 inhibitor results in decreased cancer cell proliferation and successful inhibition of the CXCL-CXCR2 pathway." (PMID 36986488, 2023). "It is worth developing CXCR2 targeting strategies to modulate the spleen immunity to improve cancer prognosis in preclinical studies." (PMID 37210553, 2023).
cancer (continued). "Upregulated CXCR2 signalling is found in numerous inflammatory, autoimmune and neurodegenerative diseases, as well as in cancer." (PMID 36903345, 2023). "Both CXCR2 and CCR2 have been associated with chemoresistance in multiple cancer types, including HGSOC." (PMID 37509311, 2023). "Chemokines, such as CCL28, CXCL8, and CXCL16, and chemokine receptors, including CCR1, CCR8, and CXCR2, were positively linked to DLAT expression in various cancers." (PMID 37199628, 2023). "Targeting CXCR2 by small molecule inhibitors will provide a new therapeutic strategy for advanced cancer treatment." (PMID 37892995, 2023). "Altogether, these results suggest that galectin-3 regulates cancer stemness, and induces cancer-cell intrinsic inflammation by upregulating CXCR2, thereby increasing tumor progression." (PMID 36873388, 2023). "CXC-chemokine receptor 2 (CXCR2) expression was found to be down-regulated on circulating monocytes of cancer patients." (PMID 37403022, 2023). "The mechanism of ACKR1 regulating pro-cancer chemokine signaling involves interplay between endothelial cells and erythrocytes that influences the activation of GPCRs CXCR2 and CXCR3." (PMID 37006247, 2023). "The depletion or blocking of CXCR2 signaling in the neutrophil inhibits cancer development and suppresses angiogenesis." (PMID 37892995, 2023). "The CXCL5/CXCR2 axis stimulates bone colonization, which is also a step for cancer cell stability in bone." (PMID 36674719, 2023). "Interactions between interleukin (IL)-8 and its receptors, CXCR1, and CXCR2, serve crucial roles in inflammatory conditions and various types of cancers." (PMID 35202450, 2022). "The other phenotypic molecule identified in M‐MDSC‐like response was CXCL5, which in cancer, acts as the chemoattractant for CXCR2‐expressing MDSCs, thus promoting MDSC recruitment and infiltration into tumors." (PMID 35285058, 2022). "CXCR2 plays an important role in cancer processes, a fact which can potentially be used in designing effective anti-cancer therapies." (PMID 35216283, 2022). "Abnormal elevations of CXCL5 and/or CXCR2 proteins have been noted in as many as 14 distinct malignant tumor types, including but not limited to CRC,263, 264 nonsmall cell lung cancer, breast cancer, bladder cancer, nasopharyngeal carcinoma, and so on." (PMID 35702353, 2022). "In the setting of cancer, the CXCR2 axis plays a dominate role in neutrophil recruitment into the TME." (PMID 35328639, 2022). "Much better research was undertaken on the regulation of CXCR2 expression by miRNA, a very significant factor in cancer." (PMID 35216283, 2022). "In this section, we briefly report an overview of investigational drugs targeting IL-8 and its receptors CXCR1/CXCR2, and discuss their therapeutic potential in the field of cancer resistance." (PMID 36591453, 2022). "The importance of the CCL2/CCR2 and CXCL8/CXCR2 axes in various cancers has led to the development of several small-molecule inhibitors that target the two axes." (PMID 36403057, 2022). "Patients with both CXCL1- and CXCR2-positive cancer (n = 28) had significantly better prognoses than those with CXCL1- and/or CXCR2-negative cancer (n = 132) (p = 0.042)." (PMID 35377900, 2022). "Macrophage migration inhibitory factor (MIF) secreted by CSCs inhibits anti-cancer immune responses via the CXCR2 pathway, increasing MDSC arginase-1 (ARG-1) expression and inhibiting CD8+T cell migration." (PMID 35269786, 2022). "Both the CXCR1 and CXCR2 chemokine receptors are prognostic biomarkers in many types of human cancers." (PMID 36091114, 2022). "Current research works are increasingly focusing on CXCR2 antagonism in therapeutic strategies for cancer and related diseases." (PMID 35158784, 2022). "Another study has shown that CXCL8 induces the production of NETs through communicating with CXCR2, which, in turn, promotes cancer cell proliferation and migration." (PMID 36091114, 2022).
cancer (continued). "In an attempt to fill this gap, the aim of this review is to provide an insight into the activity of CXCR2—its expression, activation, signal transduction, and involvement in cancer." (PMID 35216283, 2022). "We show that IL-22 regulated pro-inflammatory pathways are involved in microbial recognition, cancer and immune cell chemotaxis; most prominently those involving CXCR2+ neutrophils." (PMID 36192482, 2022). "Another mechanism is that YAP1/TEAD directly upregulates CXCL5 in cancer cells to recruit CXCR2-expressing MDSCs, leading to decreased infiltration of CD8+ T cells." (PMID 36479120, 2022). "In this article we present a comprehensive review of literature concerning the role of CXCR2 in cancer." (PMID 35216283, 2022). "Endothelial cell-generated TNF-α then triggers CXCL1/2 expression by cancer cells, which subsequently recruits CD11b+Gr1+ myeloid-derived suppressor cells that express CXCR2 (the receptor for CXCL1/2)." (PMID 36241629, 2022). "The CCL2/CCR2 and CXCL8/CXCR2 axes play an essential role in the malignant progression of tumors and act as novel targets for cancer treatment." (PMID 36403057, 2022). "Studies show that cancer patients with high levels of CXCR2 have low overall survival and poor prognosis." (PMID 33747948, 2021). "One such axis is mediated by C-X-C motif chemokine receptor 2 (CXCR2), a typical G-protein-coupled receptor that is shown to be associated with chemoresistance in several cancers." (PMID 34831316, 2021). "Although CXCR2 promotes neutrophil migration into pro-cancer sites, knockdown of CXCR2 in neutrophils increases ROS production and exerts pro-cancer effect." (PMID 34674757, 2021). "This further reinforces the importance of Cxcr2 in neutrophil function in cancer progression and opens the door for a deeper analysis of Cxcr2 properties." (PMID 34070438, 2021). "Inhibition of CXCLs/CXCR-2 axis was recognised as a potent treatment target to either contain cancer cell growth and spread or improve ICB efficiency, according to many preclinical experiments." (PMID 34336101, 2021). "CXCR2, encoded by the IL8RB gene, is a seven-transmembrane G protein-coupled receptor (GPCR) that exists on the cell membrane of endothelial and cancer cells." (PMID 34238119, 2021). "A recent study showed that cancer-educated bone marrow mesenchymal stem cells (BMSCs) do not only attract cancer cells into the circulation for distant metastasis via CXCL5/CXCR2 but also induce bone marrow-derived PMN-MDSCs." (PMID 34689842, 2021). "Due to the potent inhibition for neutrophils recruitment, CXCR2 inhibitors were initially used in respiratory diseases and gradually in cancer." (PMID 33814009, 2021). "The aim of our study was to evaluate the usefulness of serum CXCL8 and CXCR2 concentrations as biomarkers in the diagnosis and progression of this cancer." (PMID 34680333, 2021). "CXCR2 produced by cancer cells induce neutrophil extracellular traps, which interferes with immune cytotoxicity." (PMID 34840630, 2021). "Taken together, CXCL1/CXCR2 is involved in the development of neuropathic, inflammatory, and cancer pain." (PMID 33531894, 2021). "CXCLs/CXCR-2 axis is a vital chemotactic factor in cancer, known for the conscription of immunosuppressive myeloid cells from peripheral blood lesions or BM." (PMID 34336101, 2021). "The chemokines which act through CXCR1 and CXCR2 participate in numerous cancer processes, and therefore CXCR1/2 inhibitors as well as CXCR2 inhibitors, are considered as potential anticancer drugs." (PMID 33467722, 2021). "Depletion of neutrophils or blockade of CXCR2 signaling to affect neutrophil recruitment inhibits cancer growth and reduces angiogenesis." (PMID 34674757, 2021). "For this reason, CXC chemokines and their receptors are a convenient therapeutic target in the treatment of cancer, with most clinical and preclinical studies focusing on CXCR2 and CXCR4 receptors and their ligands." (PMID 33467722, 2021).